CD4 (CD4 molecule)
Diseases named in the same sentence as CD4 in open-access papers (continued):
Sharing a sentence is not in itself a finding about the gene and the disease.
melanoma (continued). "Adoptively transferred, naïve transgenic CD4 T cells with anti-melanoma reactivity acquired the ability to control autologous tumors after differentiating into cytolytic effectors." (PMID 34201655, 2021). "When CD8 T cells were depleted from melanoma, TILs and the remaining T cells (median 89% CD4 T cell composition assessed by flow cytometry) were assayed for tumor reactivity; about 20% showed tumor reactivity as assessed by IFNγ production." (PMID 34140957, 2021). "Along with the in vivo evidence, FACS assays focusing on effector T cells demonstrated enhanced TILs, especially CD8+ T cells and CD4+ T cells in [212Pb]VMT01-treated melanoma tumors, indicating strong immunogenic effect of [212Pb]VMT01 α-TRT." (PMID 34359580, 2021). "Since FlowSOM assigned Tregs to the same metacluster as other CD4+ T-cell populations in melanoma, Treg clusters were analyzed separately by defining them as one metacluster." (PMID 34071888, 2021). "Previous reports have described increased frequencies of circulating and intratumoral Tregs defined either as FoxP3+CD4+ or CD25+FoxP3+CD4+ T cell subsets for canine melanomas by either flow cytometry analysis or immunohistochemistry (IHC)." (PMID 34926643, 2021). "The capacity of cytotoxic CD4+ T cells to kill tumor has also been demonstrated in melanoma patients." (PMID 34910940, 2021). "In melanoma patients who received Ipilimumab (together with GM-CSF), elevated levels of CD4+CD127lowPD-1-cells were found in the blood of responders, but not non-responder individuals." (PMID 33546283, 2021). "An adaptive design based on toxicity and durable CD4+ T cell immune response (dRsp) was used to assign participants with resected stage IIA-IV melanoma to one of four study regimens." (PMID 33479025, 2021). "Intratumoral CD4+ T cells in Braf/Pten melanoma-bearing mice express a glucose-deprivation transcriptional signature, suggesting that they experience glucose deprivation in vivo and that their glycolysis is indeed restricted." (PMID 34079545, 2021). "Peptide vaccines designed to stimulate melanoma-reactive CD4+ T cells can induce T cell and antibody (Ab) responses, associated with enhanced overall survival." (PMID 33479025, 2021). "Others believed that CD4+ GZMB+ T cells mediated the recruitment of immune cells in melanoma through the release of inflammatory cytokines and chemokines, which would explain the increase infiltration of immune cells in the central tumor." (PMID 34631551, 2021). "Hepatitis was correctly predicted in 5 of 6 CMV IgG+ CD4+ TEM≥16% melanoma patients, which corresponds to a PPV of 83% and NPV of 80%." (PMID 34868015, 2021). "Recent data indicate that TGFβ, either through acting as a surface-bound ligand on Tregs or via increasing the CD4+Treg/CD4+Th ratio, impairs the anti-tumor response in melanoma and other skin cancers via regulatory T cells." (PMID 34789823, 2021). "Vaccines designed to induce a CD4 response have shown significant promise in improving clinical outcomes in subgroups of patients with melanoma and breast cancer." (PMID 35095898, 2021). "The comparison of our protein set with the FunRich database of protein expression sites evidenced significant enrichments in melanoma and immune cells, including neutrophils, monocytes, B cells and CD4 and CD8 T cells." (PMID 34439311, 2021). "With this setup, we monitored antigen-specific interactions between individual CD4 T cells and melanoma cells, used as a target." (PMID 34064410, 2021). "In these mice, CD4+ T cells expanded and acquired cytotoxic activity, which is in line with similar results in mouse models of melanoma." (PMID 33526861, 2021). "In melanoma, patients with a high TILs score (score 3 versus score 1 and 2) had a significantly lower frequency of circulating PD-L1+ CD4+ T-cells and PD-L1+ PD-1+ CD4+ T-cells." (PMID 34071888, 2021).
melanoma (continued). "While the total number of CD4+ T cells (CD45+ CD3+ CD4+) was not significantly different, that of CD4+ regulatory T cells (CD45+ CD3+ CD4+ FoxP3+) was significantly decreased in in AR-silenced YUMM1.7 melanomas." (PMID 33112375, 2021). "For 119 melanoma specimens, analysis of 78 ICH genes revealed association among genes with nonspecific increase of multiple immune cell subsets: CD45+, CD8+ and CD4+ T-cells, CD20+ B-cells, CD138+ plasma cells, and CD56+ NK-cells." (PMID 34454518, 2021). "Intralesional T-VEC has been associated with an increase in melanoma-specific CD8 T cells and a corresponding decrease in suppressive immune cells, such as CD4+ FoxP3+ regulatory T cells and MDSCs within the tumor microenvironment." (PMID 34680282, 2021). "Utilizing our mixed BMC model, melanoma tumor-bearing mice were adoptively transferred with IL-21-producing CD4+ T cells." (PMID 33809259, 2021). "Xenogeneic DNA immunization with xenogeneic human TRP-2 (hTRP2) DNA immunization prevented local recurrence and the development of metastases in a mouse model of minimal residual melanoma by a mechanism requiring CD4( +) and CD8( +) T cells." (PMID 33156394, 2021). "In an initial study, neoantigen-reactive CD4 T cells were detected in four out of five melanoma patients analyzed, including subjects who had a clinical response after adoptive T cell therapy." (PMID 34064410, 2021). "There has been however much attention given to MHC class II expression in various cancer types such as colorectal, cervical, lung, breast, melanoma and pancreatic cancer, pointing also to the significance of CD4+-mediated anti-tumor responses." (PMID 34335558, 2021). "The proportion of the most of immune-related cells in metastatic melanoma was higher than in primary melanoma, specifically B cells, CD4+ T cells, CD8+ T cells, and DCs." (PMID 33869027, 2021). "In the present study, we scrutinized the impact of the combined BRAF/MEK inhibition on tumor infiltrating T cells in melanoma demonstrating an increased presence of CD4+ and CD8+ T cells upon therapy." (PMID 33275172, 2021). "In contrast, enhanced FENDRR expression expanded CD4+ and CD8+ T cells and caused higher production of pro-inflammatory cytokines in C26 tumors compared to B16F10 melanoma tumors in vivo." (PMID 34200642, 2021). "CD8+ T cell and CD4+ Teff to Treg cell ratios are predictive of therapeutic efficacy of treatment in the B16 melanoma model." (PMID 33974041, 2021). "The group also identified elevated numbers of this same CD4+ T cell subset in melanoma patients responding to anti-CTLA-4 antibody treatment, compared with non-responders." (PMID 34141724, 2021). "In three murine models of melanoma (B16F10), breast (4T1) and colon (CT26) cancer, the majority of the mutated neo-epitopes were recognized by CD4+ T cells, and vaccination with such mutations elicit robust tumor rejection." (PMID 34012451, 2021). "In a report from another group, flagellin derived from Salmonella typhimurium FliCi combined with MHC class II-restricted P10 peptide inhibited lung metastasis and activation of tumor-specific CD4(+) T cells in a murine melanoma model." (PMID 34207850, 2021). "The role of CD8+ and CD4+ TILs as predictive factors for anti-PD-1 therapy was evaluated in patients with NSCLC and melanoma, and an association was found between CD8+/CD4+ TIL ratios and an increased response in both cancers." (PMID 35008273, 2021). "A significantly higher proportion of infiltrating B cells, CD4+ and CD8+ T cells, and macrophages was found in melanomas with a positive association with the AR gene-silencing signature than in those with a negative association." (PMID 33112375, 2021). "More recently, lung TILs expanded from NSCLC patients were found to consist of a higher number of CD4 T cells when compared to melanoma TILs that are enriched for CD8 TILs." (PMID 34140957, 2021).
melanoma (continued). "Here the authors show in a preclinical melanoma model that anti-CD4 treatment as a post-conditioning regimen enhances the anti-tumor efficacy of ACT by promoting the expansion of IL-18Rαhi CD8+ T cells." (PMID 34493727, 2021). "In the two monotherapy sets (GBM pembro and melanoma nivo arm), we observed that similar proteins are positively correlated with immune neighbor number, including β2M, CD4, CD45RO, and PD1." (PMID 34188042, 2021). "In an aggressive B16F10 murine melanoma model, IL-21 secretion stimulated by CD4+ TH cells drives CD8+ T cell differentiation towards CX3CR1+ cytotoxic effector phenotype and anti-tumor activity." (PMID 34012451, 2021). "Melanoma patients with a higher abundance of B cells, CD4+ T, and CD8+ T cells had a longer overall survival with or without combining the 20 patients with liver and lymphnode metastases." (PMID 34054849, 2021). "Particularly, IGF2BP3 CNV has evidently correlated with immune infiltration in melanoma, including B cells, CD4 + T cells, CD8 + T cells, macrophages, neutrophils and dendritic cells." (PMID 34446007, 2021). "Approximately 20% of TIL products were shown to contain antitumor CD4+ effectors in melanoma patients, although little attention was given to CD4+ T cells in the past." (PMID 33546283, 2021). "CD28 expression is declined on metastatic melanoma cells while its expression shows an increase in CD4+ lymphocytes that are migrating toward tumors." (PMID 32902664, 2021). "Treg cells in the B16-F10 melanoma tumor model showed increased infiltration after anti-PD-1 while in a low CD8/CD4 ratio, suggesting immune escape in the checkpoint blockade." (PMID 33936081, 2021). "In both groups of mice, reduced activation of the CD4+ T cells and TILs in Ret melanoma and the MC38 colon cancer models indicated significantly reduced efficacy of CTLA-4 antibody." (PMID 33783613, 2021). "Our group has previously shown that IL-21-producing CD4+ T cells provide critical help to promote the generation of effector CX3CR1+ CD8+ T cells in a preclinical melanoma model." (PMID 33809259, 2021). "A meta-analysis of all-sites melanoma showed a favorable role of CD4+, CD8+, and FOXP3+ as prognostic factors." (PMID 33916279, 2021). "Vaccination induced strong multi-functional CD4+and CD8+ T-cell responses in patients with high risk melanomas." (PMID 35959968, 2021). "MHC-II molecules, particularly HLA-DRA, are critical for antigen presentation to CD4+ T cell and required for antiPD-1/PD-L1 activity in melanoma; agents that induce MHC-II positivity can be combined with PD-1/PD-L1-targeted therapy to improve response rates." (PMID 33747255, 2021). "We previously reported that pre-therapy expansion of cytomegalovirus (CMV)-reactive CD4+ effector memory T cells (TEM) predicts ICI-related hepatitis in a subset of patients with Stage IV melanoma given αPD-1 and αCTLA-4." (PMID 34868015, 2021). "The results showed that melanoma was highly infiltrated by CD4+ T cells, NK cells, dendritic cells, and neutrophils but poorly by cells of B cells, CD8+ T cells, monocytes, and macrophages in comparison with colorectal cancer." (PMID 34054849, 2021). "Presently, the roles of naive B cells, memory resting CD4 T cells, and memory B cells in the development of melanoma are not well understood." (PMID 33758620, 2021). "In the adoptive cell therapy (ACT) setting, melanoma-specific TCR transgenic CD4+ T cells produced both IFN-γ and GzmB within tumors, suggesting that these cells have both helper and cytotoxic activities (Th-ctx)." (PMID 31924474, 2020). "A prior study reported that there was divergent DNAM-1 expression in Tregs and CD4+ effector T cells in melanoma patient TILs, demonstrating that different mechanisms are involved in regulating DNAM-1 expression in different functional T cell subsets." (PMID 32802845, 2020).
melanoma (continued). "Melanoma patients who developed immune-related adverse events under immune checkpoint CIT also presented with expanded granzyme-expressing CD4+ and CD8+ T cell populations." (PMID 32226027, 2020). "Accordingly, a similar correlation between Tregs (CD4+FoxP3+) and CD11b+ cells was detected in IDOhigh melanoma cell suspensions as compared to IDOlow samples." (PMID 32782249, 2020). "In line with our findings, the inoculation of melanoma cells in mice was reported to decrease B and CD8α + T lymphocytes, increase CD4+ T lymphocytes and NK cells percentages and activate markers of NK in blood." (PMID 32180771, 2020). "Of note, and as expected from the results shown before, cytotoxicity of CD4+ T cell transduced with the 4/134 cTCR against NY-ESO-1+ HLA-A*02+ D05 melanoma cells was considerably lower as compared to CD4+ T cell transduced with the 4/76 cTCR." (PMID 32903281, 2020). "Currently, only a limited number of studies have investigated the prognostic potential of CD4+ TIL enumeration in melanoma using IHC or IF." (PMID 33013886, 2020). "Depending on the analysed locus (promoter, gene body) we found region-dependent significant LAG3 methylation differences between monocytes, B cells, CD8+ and CD4+ T cells, regulatory T cells, melanocytes, and melanoma cell lines." (PMID 32861198, 2020). "Previous studies indicated a favorable role of CD4+ tumor-infiltrating lymphocytes in melanoma, colon, breast, and HCC." (PMID 33552954, 2020). "Similar enrichments were observed for experimental gene sets of IL-1β-, TNFα-, or TGF-β1-response induced in human melanoma cell lines, primary endothelial cells, fibroblasts, melanocytes, or CD4+ T cell clones." (PMID 32917858, 2020). "In particular, reductions in peripheral CD4+ T lymphocytes are commonly observed in advanced cases of pancreatic cancer, melanoma, non-Hodgkin lymphoma, sarcoma, hepatocellular carcinoma, and breast cancer." (PMID 33267869, 2020). "The prognosis of melanoma was significantly negatively correlated with the infiltration of CD4+ T cells, CD8+ T cells, dendritic cells, neutrophils and macrophages." (PMID 33585219, 2020). "In another tumor, C3aR expression seems to contribute to melanoma carcinogenesis through the inhibition of neutrophils and CD4+T cell response." (PMID 32345771, 2020). "Conversely, conjugation of another melanoma antigen, gp100, with glycans revealed its potential to induce a CD4+ T cell response through the MHC class II cross-presentation pathway." (PMID 32150821, 2020). "Experiments have shown that CD8+ T cells and CD4+ T cells play a role in the treatment of breast cancer, colon cancer, etc., especially in melanoma." (PMID 33585219, 2020). "A study of neoadjuvant Ipilimumab in advanced melanoma showed an increased infiltration of memory CD4+ and CD8+ T cells in the TME." (PMID 32793228, 2020). "For several types of human cancers, including melanoma, non-small-cell lung, gastric and ovarian cancers, Treg cells account for 10–50% of tumor infiltrated CD4 T cells compared with 2–5% of CD4 T cells in the peripheral blood of healthy individuals." (PMID 32477338, 2020). "Particularly, GD3 expressed on melanoma is known to activate both CD4+CD8− NKT and CD4−CD8− NKT cells to produce IL-4, whereas CD4− CD8− NKT cells also react with GM3 as a tumor-associated suppressive glycolipid in a CD1d-restricted manner." (PMID 32231116, 2020). "Transcriptional analysis of Th-ctx melanoma-reactive CD4+ T cells revealed high Prdm1 and Tbx21 expression and decreased expression of Tfh signature genes." (PMID 31924474, 2020). "CD103+ cDC1 vaccination i.t. in murine melanoma or osteosarcoma promotes selective accumulation of IFN-γ+ CD4+ T cells (T helper 1, Th1) and IFN-γ+ CD8+ T cells within tumors." (PMID 31947933, 2020). "We used triple-color immunohistochemistry to evaluate Foxp3 and GzmB expression in CD4+ TILs in patients with advanced melanoma prior to therapy and 3 weeks post-treatment with ipilimumab and melphalan." (PMID 31924474, 2020).
melanoma (continued). "In the studies of melanoma, patients with a higher degree of CD4+ tumor-infiltrating lymphocytes tend to have more favorable outcome." (PMID 33273963, 2020). "In contrast, our analysis supports the idea that more infiltration of activated CD4+ T cells and central memory CD4+ T cells were associated with dismal prognosis in HCC, which is similar to several studies on melanoma, colo-rectal, and breast cancers." (PMID 33552954, 2020). "On the other hand, TSA suppresses the growth of B16-F0 melanoma through inhibition of CD4 T cell apoptosis by specifically down-regulating FASL expression on tumor-infiltrated CD4 T cells." (PMID 32560120, 2020). "Melanoma patients also harbored an enhanced fraction of CD4+Foxp3+ regulatory T cells, while their effector T cells expressed lower levels of the activation marker HLA-DR." (PMID 33344043, 2020). "have confirmed the favorable prognostic role of the CD3+, CD4+, CD8+ TILs in melanoma patients’ overall survival as well as the association between TIL presence and improved overall survival." (PMID 33117345, 2020). "In conflict with previous evidence, Zhang and co-authors highlighted that the expression of SHP-2 in CD4+ T cells exerts tumor-suppressing effects on melanoma." (PMID 33003469, 2020). "Consistently, in melanoma lung metastasis model, we found a higher ratio of effector CD4 T cells to Treg cells in tumor compared with WT counterparts." (PMID 32477338, 2020). "By using the immunogenetic dataset from MSKCC group 39, we also noticed patients with mutations in CDH6 or other core CDH genes showed more γδT cell recruitments in melanoma lesions with more activated CD4+ memory T cells and higher cytolytic scores." (PMID 33204327, 2020). "In previous studies, multi-target long peptides, or RNA-based vaccine have been used to induce CD8+ (and CD4+) T-cell responses in melanoma patients." (PMID 31156619, 2019). "NDV infection of human melanoma cells was reported to break tolerance of a melanoma-specific CD4+ T helper cell line." (PMID 31480379, 2019). "When cocultured naïve CD4+ T cells isolated from human peripheral blood mononuclear cell with melanoma cells and tumor-derived fibroblasts, the percentage of Th17 cells was higher than in the medium alone." (PMID 30800130, 2019). "The lack of CD4 T cells did not notably impair anti-tumor immune responses in immunized mice, the melanoma growth and mouse survival being comparable in WT and in CD4 T-cell-depleted mice." (PMID 31333674, 2019). "Flow cytometry revealed two DP T-lymphocyte subpopulations, i.e., melanoma-associated CD4+/CD8high T-lymphocytes in peripheral blood and CD4+/CD8high TILs in melanoma tissue (together with CD4−/CD8+ T-lymphocytes), which expanded during melanoma regression." (PMID 31717496, 2019). "Percentages of IFN-γ producing cells in CD8+ and CD4+ T cells against a panel of melanoma and ovarian cancer cell lines were determined by intracellular cytokine staining." (PMID 30626427, 2019). "In anti-PD-1-treated melanoma patients, MHC-II positivity in addition to ubiquitous MHC-I expression has been associated with CD4+ and CD8+ T cell infiltrates and has been predictive for the response to PD-1 blockade and overall survival." (PMID 31703604, 2019). "In contrast to highly restricted repertoires of CD8+ T cells, which were seen in all analyzed patients, we observed that the degree of CD4+ blood T-cell repertoire restrictions varied among melanoma patients." (PMID 31275310, 2019). "Emphasizing the power of this approach, transcriptomic patterns identified in the present study are also found in CD4+ T cells infiltrating human tumors and correlate with response to checkpoint therapy in human melanoma." (PMID 31801070, 2019). "As in healthy controls, CD8+ T-cell repertoires of melanoma patients were more restricted than those of CD4+ T cells (p = 0.000063, p = 0.000064, respectively)." (PMID 31275310, 2019).